INPP4A (inositol polyphosphate-4-phosphatase type I A)
Description:
Catalyzes the hydrolysis of the 4-position phosphate of phosphatidylinositol 3,4-bisphosphate (PtdIns(3,4)P2). Also catalyzes inositol 1,3,4-trisphosphate and inositol 1,4-bisphosphate (By similarity). Antagonizes the PI3K-AKT/PKB signaling pathway by dephosphorylating phosphoinositides and thereby modulating cell cycle progression and cell survival (By similarity). May protect neurons from excitotoxic cell death by regulating the synaptic localization of cell surface N-methyl-D-aspartate-type glutamate receptors (NMDARs) and NMDAR-mediated excitatory postsynaptic current (By similarity). [Isoform 4]: Displays no 4-phosphatase activity for PtdIns(3,4)P2, Ins(3,4)P2, or Ins(1,3,4)P3.
Synonyms: INPP4; NEDGQS; TVAS1
Tractability: Antibody: UniProt places it where antibodies can reach, with high confidence; its Gene Ontology location is reachable by antibodies, with medium confidence. PROTAC: ubiquitination databases record sites on it; its protein half-life has been measured.
Gene: Protein-coding gene on chromosome 2 (98,444,246 to 98,594,392, forward strand). Ensembl gene ENSG00000040933.
Subcellular location: Early endosome membrane; Recycling endosome membrane; Cell membrane; Nucleus; Cytoplasm; Postsynaptic density
Subcellular location (Human Protein Atlas): Nuclear membrane; Nucleoplasm
Pathways (Reactome):
Metabolism: Synthesis of IP2, IP, and Ins in the cytosol; Synthesis of PIPs at the early endosome membrane; Synthesis of PIPs at the plasma membrane
Gene Ontology:
Molecular function: phosphatidylinositol-3,4-bisphosphate 4-phosphatase activity; protein binding; inositol-1,3,4-trisphosphate 4-phosphatase activity; inositol-3,4-bisphosphate 4-phosphatase activity
Biological process: inositol phosphate metabolic process; phosphatidylinositol biosynthetic process; signal transduction; phosphatidylinositol-3-phosphate biosynthetic process; phosphorus metabolic process
Cellular component: cytoplasm; early endosome membrane; nuclear membrane; nucleoplasm; nucleus; plasma membrane; recycling endosome membrane; cytosol; postsynaptic density; organelle
Genetic constraint (gnomAD): Loss-of-function variants: 22 observed, 76.34 expected, observed/expected ratio (o/e) 0.29, 90% interval 0.2 to 0.41. The upper end of that interval is the gene's LOEUF score, 0.41, which puts it in group 1 of 6, group 1 being the genes least tolerant of losing a copy. Missense variants: 771 observed, 1,031 expected, observed/expected ratio (o/e) 0.75, 90% interval 0.7 to 0.79. Synonymous variants: 416 observed, 406.5 expected, observed/expected ratio (o/e) 1.02, 90% interval 0.94 to 1.11.
Homologues: Orthologues: chimpanzee INPP4A (99% identical), guinea pig INPP4A (98% identical), macaque INPP4A (97% identical), dog INPP4A (97% identical), pig INPP4A (97% identical), mouse Inpp4a (96% identical), rabbit INPP4A (94% identical), rat Inpp4a (90% identical), tropical clawed frog inpp4a (87% identical), zebrafish inpp4ab (77% identical), zebrafish inpp4aa (75% identical). Paralogues in human: INPP4B (40% identical).
Diseases named in the same sentence as INPP4A in open-access papers:
INPP4A is named in the same sentence as 40 diseases in open-access papers, as found by Europe PMC text mining. Sharing a sentence is not in itself a finding about the gene and the disease. The quoted sentences say what the papers report.
asthma (8 papers, 2009 to 2025). "Previous studies have demonstrated that polymorphisms in the INPP4A gene are associated with asthma in humans, possibly due to reduced protein stability." (PMID 32631807, 2021). "For example, loss of function mutations in the principal inhibitory phosphatases SHIP, PTEN, and INPP4A, are associated with asthma, and knockdown of INPP4A induces airway remodeling and hyperresponsiveness." (PMID 24204385, 2013). "Moreover, INPP4A gene variants were found to be associated with metabolic syndrome and asthma, and very interestingly INPP4A is also one of the insulin-signaling molecules." (PMID 23840225, 2013). "Taking lead from differentially expressed genes in a microarray study in ovalbumin sensitized mice, we have recently identified inositol polyphosphate 4-phosphatase type I (INPP4a), a novel gene associated with asthma, using population genetics as well as in-vitro and in-vivo studies." (PMID 19419542, 2009). "Previously, we have demonstrated the implications of INPP4A downregulation, especially the secretory form, in the regulation of airway inflammation and sub‐epithelial fibrosis during asthma." (PMID 38720166, 2024). "Extracellular vesicle (EV)-mediated transfer of inositol polyphosphate 4-phosphatase type I A (INPP4A), a lipid phosphatase and an asthma candidate gene, functions to restrain the proliferative capacity of fibroblasts by dampening PI3K/Akt signaling." (PMID 32509793, 2020). "Antibody-mediated neutralization of this vesicular INPP4A induced airway hyperresponsiveness, with prominent airway remodeling, subepithelial fibroblast proliferation, and collagen deposition in a murine model of asthma." (PMID 33915715, 2021). "Notably, it was predicted that miR-223-3p might directly target inositol polyphosphate 4 phosphatase (INPP4A), a gene known to be involved in asthma and allergic disorders." (PMID 32631807, 2021).
Intellectual disability (3 papers, 2022 to 2023). "INPP4A has been implicated in multiple neurological conditions, namely schizophrenia, autism, epilepsy, and intellectual disability." (PMID 36449109, 2023). "Several neurological diseases with diverse phenotypes, such as ataxia with cerebellar atrophy or intellectual disability without brain malformation, are caused by mutations in INPP4A, which encodes a phosphoinositide phosphatase." (PMID 37415561, 2023).
atopic asthma (2 papers, 2021 to 2024). An asthma that is characterized by symptoms that are triggered by an allergic reaction caused by inhaled allergens such as dust mite allergen, pet dander, pollen and mold. "The earliest report for the role of INPP4A in the lung showed the genetic association of INPP4A with atopic asthma." (PMID 38720166, 2024). "Moreover, INPP4A is involved in the regulation of atopic asthma and may open new avenues for therapeutic intervention by modulating the PI3K-Akt pathway." (PMID 32631807, 2021).
Bladder Cancer (2 papers, 2021 to 2024). "Over-expressed miRNA-940 promoted proliferation, migration, and invasion of bladder cancer cell and inhibited cell apoptosis by mediating INPP4A or GSK3β and activating the Wnt/β-catenin pathway." (PMID 34338136, 2021).
esophageal squamous cell carcinoma (2 papers, 2016 to 2025). Esophageal squamous cell carcinoma (ESCC) is a type of esophageal carcinoma (EC) that can affect any part of the esophagus, but is usually located in the upper or middle third. "Furthermore, high levels of miR-508, a microRNA which targets multiple phosphatases including PIPP, PTEN and INPP4A, correlate with clinical stage and reduced 5-year disease-free and overall survival in esophageal squamous cell carcinoma patients." (PMID 41408399, 2025). "In esophageal squamous cell carcinoma (ESCC), the elevated miR-508-3p correlates with poor survival and activated PI3K/Akt signaling by targeting inositol polyphosphate-5-phosphatase J (INPP5J), phosphatase and tensin homologue (PTEN) and inositol polyphosphate 4-phosphatase type I (INPP4A)." (PMID 26801246, 2016).
pancreatic cancer (2 papers, 2019). "Additionally, miR-935 participates in cell proliferation, migration and apoptosis by reacting with its target, INPP4A, in pancreatic cancer." (PMID 31049029, 2019).
airway hyperresponsiveness (1 paper, 2024). "Functional studies have highlighted the importance of INPP4A in maintaining normal lung structure, and loss of cellular and secretory INPP4A in naïve mice developed spontaneous airway hyperresponsiveness and airway remodeling." (PMID 38720166, 2024).
Ataxia (1 paper, 2023). Ataxia refers to impaired coordination of voluntary muscle movement. "En1-Cre;Inpp4a cKO mice exhibited ataxia and a lifespan of only 4–5 weeks." (PMID 37415561, 2023).
Cerebellar atrophy (1 paper, 2023). Cerebellar atrophy is defined as a cerebellum with initially normal structures, in a posterior fossa with normal size, which displays enlarged fissures (interfolial spaces) in comparison to the foliae secondary to loss of tissue. "These behavioral and histological defects are similar to those of Inpp4aΔEx23 KO mice, indicating that disruption of Inpp4a in the cerebellum is the leading cause of cerebellar atrophy and movement disorder in Inpp4aΔEx23 KO mice." (PMID 37415561, 2023). "In contrast, Inpp4a mutants lacking exon 23, which encodes a C-terminal phosphatase domain (Inpp4aΔEx23 KO mice), exhibited striatal degeneration and cerebellar atrophy." (PMID 37415561, 2023). "We examined two strains of Inpp4a mutant mice with distinct cerebellar phenotypes: the Inpp4aΔEx1,2 mutant exhibited striatal degeneration without cerebellar atrophy, and the Inpp4aΔEx23 mutant exhibited a severe striatal phenotype with cerebellar atrophy." (PMID 37415561, 2023).
cerebellar degeneration (1 paper, 2023). Degeneration of the cerebellum. "In the present study, we analyzed two strains of Inpp4a mutant mice with or without cerebellar degeneration." (PMID 37415561, 2023).
chronic lung disease (1 paper, 2024). According to the definitions of the American and British Thoracic Societies, including pulmonary functional tests, X-rays, and CT scans for items such as fibrosis, bronchiectasis, bullae, emphysema, nodular or lymphomatous abnormalities. "Though existing evidences suggest a critical role for INPP4A in the maintenance of lung homeostasis, its role in chronic lung diseases is relatively under explored." (PMID 38720166, 2024).
idiopathic pulmonary fibrosis (1 paper, 2024). Idiopathic pulmonary fibrosis (IPF) is a nonneoplastic pulmonary disease that is characterized by the formation of scar tissue within the lungs in the absence of any known cause. "We next proceeded to distinguish between the compensatory and pathogenic roles of INPP4A in pulmonary fibrosis." (PMID 38720166, 2024). "INPP4A's heterogeneous expression as discussed in the previous section opened up two possibilities of its role in pulmonary fibrosis, compensatory or pathogenic." (PMID 38720166, 2024). "Our analysis revealed that INPP4A is upregulated in human lung samples of idiopathic pulmonary fibrosis, compared to control lung samples." (PMID 38720166, 2024). "Before assessing the effect of INPP4A neutralization, we first checked if INPP4A secretion was altered in pulmonary fibrosis." (PMID 38720166, 2024). "With the understanding that INPP4A expression is relevant in IPF pathophysiology, we sought to investigate the therapeutic potential of experimental downregulation of INPP4A in pulmonary fibrosis." (PMID 38720166, 2024). "To understand if this was relevant to other fibrotic lung diseases, particularly IPF, we studied INPP4A expression in pulmonary fibrosis." (PMID 38720166, 2024). "To further confirm upregulated INPP4A protein expression in Bleo mice, we performed ELISA on lung homogenates, derived from mice with bleomycin induced pulmonary fibrosis and vehicle treated mice." (PMID 38720166, 2024). "Mice with bleomycin induced PF given anti‐INPP4A antibody had worsened pulmonary fibrosis in comparison to their respective controls." (PMID 38720166, 2024). "In the current study, we made an attempt to understand the regulation of INPP4A in idiopathic pulmonary fibrosis (IPF)." (PMID 38720166, 2024). "The observation that intraperitoneal treatment with anti‐INPP4A antibody increased subepithelial fibroblast proliferation and collagen deposition in both naïve mice and mice with AAI provided a strong rationale to investigate the role of INPP4A in the pathogenesis of pulmonary fibrosis (PF)." (PMID 38720166, 2024). "Fibroblasts from bleomycin injured aged mice also showed reduced INPP4A expression in comparison to fibroblasts from bleomycin injured young mice indicating attenuated INPP4A expression to be a part of transcriptional programming governing persistent lung fibrosis (GSE191208)." (PMID 38720166, 2024). "The specificity of INPP4A upregulation observed in these datasets was supported by similar findings in an independent set of lung samples from IPF and control donors collected at Mayo clinic, Rochester, USA, and from studies on bleomycin‐induced mouse models of pulmonary fibrosis." (PMID 38720166, 2024).
lung carcinoma (1 paper, 2022). "In lung cancer, genomic profiling identified a distinctive molecular signature in asbestos-exposed patients compared to not-exposed, including copy number aberrations in the 2p16, 9q33.1 and 19p13 loci and MRPL1, INPP4A, SDK and SEMA5B somatic mutations." (PMID 35755315, 2022).
cancer (4 papers, 2019 to 2025). A tumor composed of atypical neoplastic, often pleomorphic cells that invade other tissues. "In cancer, INPP4A and INPP4B are considered to act as tumor suppressors by inhibiting the PI3K/AKT signaling pathway in several tumor types including breast, ovary, lung, pancreatic, melanoma, and esophageal cancer." (PMID 32296634, 2020). "In addition, we identified three heterozygous candidate missense variants in known cancer susceptibility genes (BMPR1A,BRIP1, and SRC), three truncating variants in possibly novel cancer genes (CLSPN,SEC24B, SSH2) and four candidate missense variants in ACACA, NR2C2, INPP4A, and DIDO1." (PMID 30809968, 2019).
tumor (3 papers, 2019 to 2025). "In addition, that Inpp4a-/- MEF also displayed elevated pAkt levels compared to wild type after SV40 T-Large immortalization support the notion that 4-phosphatase function is tumour suppressive in part through regulation of Akt signaling." (PMID 31695845, 2019).
genetic diseases (1 paper, 2023). "Recent studies have reported human genetic diseases associated with variation in the human INPP4A gene." (PMID 37415561, 2023).
neurological diseases (1 paper, 2023). "Because homozygous mutation in the cerebellar INPP4A isoform leads to neurological disorder without central nervous system malformation, the isoform with the C2 domain and putative transmembrane domain has specific function(s) other than phosphatase activity." (PMID 37415561, 2023). "Our results indicate that the diverse phenotypes observed in Inpp4a-related neurological diseases could be due to the varying protein expression levels and retained phosphatase activity in different Inpp4a variants." (PMID 37415561, 2023).
INPP4A also shares sentences with these, for which no sentence is quoted: autism (2 papers); epilepsy (2); schizophrenia (2); allergic asthma (1); allergic rhinitis (1); basal cell carcinoma (1); brain malformation (1); breast carcinoma (1); Cushing syndrome (1); diabetes (1); esophageal carcinoma (1); lung diseases (1); melanoma (1); metabolic syndrome (1); microcephaly (1); movement disorder (1); myoclonic epilepsy (1); neurodegenerative disease (1); neurodevelopmental disorder (1); non-alcoholic fatty liver disease (1); non-small cell lung carcinoma (1); small cell lung carcinoma (1); T cell lymphomas (1).